RNU6-129P (RNA, U6 small nuclear 129, pseudogene)
Gene: Small nuclear RNA gene on chromosome 10 (83,764,358 to 83,764,464, forward strand). Ensembl gene ENSG00000212324.
Homologues: Orthologues: chimpanzee U6 (95% identical), macaque U6 (90% identical). Paralogues in human: RNU6-686P (81% identical), RNU6-961P (81% identical), RNU6-211P (80% identical), RNU6-455P (80% identical), RNU6-657P (80% identical), RNU6-746P (80% identical), RNU6-1145P (79% identical), RNU6-1316P (79% identical), RNU6-181P (79% identical), RNU6-188P (79% identical), RNU6-393P (79% identical), RNU6-753P (79% identical), and 1289 more.